ZC3H13 (zinc finger CCCH-type containing 13)
Diseases named in the same sentence as ZC3H13 in open-access papers (continued):
Sharing a sentence is not in itself a finding about the gene and the disease.
keloid (3 papers, 2024 to 2025). An irregularly shaped, elevated mark on the skin caused by deposits of excessive amounts of collagen during wound healing. "In addition, higher levels of m6A and higher expression levels of the component of the MTC ZC3H13 were found in keloid tissues and human keloid fibroblasts, linking m6A to hypertrophic scar pathogenesis." (PMID 40700032, 2025). "In the pathogenesis of keloids, the m6A regulator ZC3H13 was found to be upregulated." (PMID 39472463, 2024). "Therefore, ZC3H13-mediated HIPK2 mRNA m6A modification could promote keloid progression by the post-transcriptional regulation of HIPK2." (PMID 39472463, 2024). "ZC3H13 overexpression increased m6A modification of HIPK2 mRNA, leading to heightened mRNA stability and elevated HIPK2 expression in keloid tissues." (PMID 39472463, 2024).
thyroid cancer (3 papers, 2021 to 2025). "ZC3H13 increased the m6A modification of hsa_circ_0101050 and inhibited its expression, which in turn inhibited thyroid cancer." (PMID 39967906, 2025). "ZC3H13 overexpressed thyroid cancer cells have elevated m6A levels of IQGAP1 mRNA." (PMID 38351022, 2024).
adenomyosis (2 papers, 2020 to 2024). The growth of endometrial tissue inside the muscular wall of the uterine corpus. "From the analysis of the gene expression profile of GSE78851, we found that METTL3, ZC3H13, FTO, and YTHDC1 were all significantly decreased in the eutopic endometrium of adenomyosis patients versus controls." (PMID 32719721, 2020).
childhood asthma (2 papers, 2021). "Moreover, in another study on childhood asthma found that m6A regulators also played a crucial role, and screened five candidate m6A regulators (FMR1, KIAA1429, WTAP, YTHDC2 and ZC3H13) to predict the risk of childhood asthma." (PMID 34647423, 2021).
cutaneous melanoma (2 papers, 2021). A primary melanoma arising from atypical melanocytes in the skin. "According to the results of the multivariate Cox regression analysis, three of the seventeen m6A RNA methylation regulators were proved to be the potential prognostic factors of cutaneous melanoma, including ELF3, ZC3H13, and WTAP." (PMID 34291082, 2021).
esophageal cancer (2 papers, 2021). A primary or metastatic malignant neoplasm involving the esophagus. "From the TCGA database, we found that several m6A-associated genes, including YTHDF1, HNRNPC, ZC3H13, YTHDC2, and METTL14 were dysregulated in esophageal cancer compared to matched normal tissues." (PMID 34395102, 2021). "We found that HNRNPC, YTHDF, ZC3H13, YTHDC2, and METTL14 were dysregulated in esophageal cancer tissues." (PMID 34395102, 2021).
esophageal squamous cell carcinoma (2 papers, 2025). Esophageal squamous cell carcinoma (ESCC) is a type of esophageal carcinoma (EC) that can affect any part of the esophagus, but is usually located in the upper or middle third. "However, the precise function of ZC3H13 in the esophageal squamous cell carcinoma tumor microenvironment (TME) remains incompletely understood." (PMID 40959082, 2025). "In esophageal squamous cell carcinoma (ESCC), ZC3H13 modulates METTL14/METTL3 nuclear transport and stabilizes CXCL8 mRNA, driving M2 polarization and infiltration, thereby facilitating immune evasion." (PMID 41164187, 2025). "Given these diverse roles of ZC3H13 in regulating tumorigenesis through m6A-dependent pathways, it is reasonable to speculate that ZC3H13 may also influence esophageal squamous cell carcinoma (ESCC), particularly through modulation of the tumor immune microenvironment." (PMID 40959082, 2025).
Obesity (2 papers, 2022). Accumulation of substantial excess body fat. "In contrast, METTL15, zinc finger CCCH-type containing 13 (ZC3H13), fat mass and obesity-associated (FTO), leucine-rich pentatricopeptide repeat containing (LRPPRC), and RNA-binding motif protein 15B (RBM15B) showed widespread CNV frequency loss." (PMID 34979500, 2022).
psoriasis (2 papers, 2022 to 2024). An autoimmune condition characterized by red, well-delineated plaques with silvery scales that are usually on the extensor surfaces and scalp. "The roles of other genes, including ZC3H13, HNRNPC and YTHDC1, in psoriasis have not yet been explored." (PMID 38436011, 2024).
pulmonary fibrosis (2 papers, 2022 to 2025). Chronic progressive interstitial lung disorder characterized by the replacement of the lung tissue by connective tissue, leading to progressive dyspnea, respiratory failure, or right heart failure. "Regarding m6A writers, the methyltransferases METTL3, METTL14, and ZC3H13 have been identified as potential biomarkers for early diagnosis of pulmonary fibrosis and as prognostic indicators for patients with pulmonary fibrosis." (PMID 39756462, 2025).
atrial fibrillation (1 paper, 2023). A disorder characterized by an electrocardiographic finding of a supraventricular arrhythmia characterized by the replacement of consistent P waves by rapid oscillations or fibrillatory waves that vary in size, shape and timing and are accompanied by an irregular ventricular response. "Five feature m6A regulatory genes, ZC3H13, YTHDF1, HNRNPA2B1, IGFBP2, and IGFBP3, were determined (p < 0.05) to establish a nomogram model that can predict the incidence of atrial fibrillation with the RF model." (PMID 37435047, 2023).
bladder tumors (1 paper, 2021). "However, some m6A regulators, including METTL3, RBM15B, YTHDF1, YTHDF2, and IGFBP3, were significantly overexpressed in bladder tumors, and some m6A regulators, including METTL14, METTL16, ZC3H13, and YTHDF3, were markedly downregulated in bladder tumors." (PMID 35004726, 2021).
breast tumor (1 paper, 2020). "Besides, we analyzed the downstream carcinogenic molecular mechanisms related to METTL14 and ZC3H13 and their relationship with immune infiltration in breast tumor tissues." (PMID 33363011, 2020).
Chagas disease (1 paper, 2022). A parasitic infection caused by Trypanosoma cruzi. "ZC3H13 is involved in biological functions such as phosphoinositide metabolism, Chagas disease, propionate metabolism and transcriptional dysregulation in cancer." (PMID 35278064, 2022).
depression (1 paper, 2022). "Next, we performed differential gene analysis of m6A regulators in depression and found that FTO, RBM15B, METTL3, LRPPRC, HNRNPC, ZC3H13, and YTHDF2 were significantly upregulated in depressed rats." (PMID 35480327, 2022).
endometrial adenocarcinoma (1 paper, 2021). "In contrast, the expression of METTL14, KIAA1429, and ZC3H13 was drastically decreased in patients with endometrial adenocarcinoma." (PMID 34149936, 2021).
head and neck squamous cell carcinoma (1 paper, 2025). A squamous cell carcinoma that arises from any of the following anatomic sites: lip and oral cavity, nasal cavity, paranasal sinuses, pharynx, larynx, and salivary glands. "In head and neck squamous cell carcinoma (HNSC), the presence of HNRNPC, DNMT1, DNMT3A, ZC3H13, NSUN5, and IGF2BP2 highlights potential cross-talk between DNA and RNA methylation in immune modulation." (PMID 40565233, 2025).
laryngeal squamous cell carcinoma (1 paper, 2024). A squamous cell carcinoma that arises from the larynx. "ZC3H13 regulates the DUOX1 gene through m6A methylation modification, thereby affecting iron death in laryngeal squamous cell carcinoma." (PMID 38351022, 2024).
prostate adenocarcinoma (1 paper, 2021). "For PFS, high expression of ZC3H13 was also associated with favorable prognosis in KIRC, kidney renal papillary cell carcinoma (KIRP) and prostate adenocarcinoma (PRAD) and poor prognosis in CESC." (PMID 34497769, 2021).
prostate tumors (1 paper, 2021). "Seven regulators, including IGF2BP2, METTL3, METTL16, ZNF217, ZC3H13, RBM15B, and PRRC2A, exhibited significant correlations between CNVs and gene expression levels in prostate tumors." (PMID 34899855, 2021).
renal carcinoma (1 paper, 2021). A carcinoma arising from the epithelium of the renal parenchyma or the renal pelvis. "ZC3H13 is predictive of immune phenotype and therapeutic responses in renal carcinoma." (PMID 35003256, 2021).
schizophrenia (1 paper, 2019). A major psychotic disorder characterized by abnormalities in the perception or expression of reality. "The genetic polymorphism of ZC3H13 is associated with schizophrenia." (PMID 31452869, 2019).
thymoma (1 paper, 2021). A neoplasm arising from the epithelial cells of the thymus. "Similarly, for CSS, high expression of ZC3H13 was still associated with favorable prognosis in KIRC, KIRP, and thymoma (THYM) and poor prognosis in CESC." (PMID 34497769, 2021).
tumor (87 papers, 2020 to 2026). "As studies have generally found decreased expression of ZC3H13 to be associated with tumor size, metastasis, and prognosis of PTC, future studies should explore its potential as a therapeutic target and biomarker for PTC." (PMID 40243425, 2025). "TRDMT1 and ZC3H13 have also been implicated in modulating mRNA splicing and stability, suppressing tumor progression in urological cancers." (PMID 40565233, 2025). "The m6A regulators cluster with the best prognosis had significantly increased METTL14 and ZC3H13 expression and was characterized by low mutation rate, tumor heterogeneity, and neoantigens." (PMID 34531875, 2021). "We found that KIAA1429, ZC3H13, and RBM15B presented the highest CNV frequency, and ZC3H13 exhibited a loss in copy number, which corresponded to the expression level of ZC3H13 in tumor samples." (PMID 34733275, 2021). "Among them, a mutation in the "writer" gene ZC3H13 was the most frequent and was detected in 64 tumor samples with 114 mutations, accounting for 10.12% of the total m6A gene mutations." (PMID 33033522, 2020). "The association between the expression level of ZC3H13 and tumor growth varies between malignancies, with ZC3H13 acting as a tumor suppressor in some cancers and thus its downregulation is associated with tumor growth, while the opposite is true in some other cancers." (PMID 40243425, 2025). "Moreover, the ZC3H13 level was significantly positively associated with tumor immune cell infiltration, biomarkers of immune cells, and immune checkpoint expression." (PMID 35278064, 2022). "Furthermore, FTO, KIAA1429, WTAP, ZC3H13 were significantly associated with tumor recurrence (P < 0.05)." (PMID 35572524, 2022). "To elucidate the oncogenic role of ZC3H13 in GC, we performed in vivo experiments and established a subcutaneous tumor model." (PMID 40774945, 2025). "The results indicated that ZC3H13 overexpression promoted the proliferation of GC in vivo, with tumor volume and weight significantly higher than that of the control group, but these effects were reversed by SNTB1 knockdown." (PMID 40774945, 2025). "Building on the evidence that m6A modification shapes tumor progression and immune evasion, we aimed to investigate the role of ZC3H13 in ESCC, with a specific focus on its regulatory effects on chemokines and macrophage polarization." (PMID 40959082, 2025). "On the other hand, emerging evidence suggests METTL14 and ZC3H13 function as tumor suppressors in triple-negative breast cancer." (PMID 41157107, 2025). "Expression overlays of six RNA modification genes selected by the LASSO Cox model (DNMT1, DNMT3A, HNRNPC, IGF2BP2, NSUN5, and ZC3H13) demonstrated variable distribution across the tumor microenvironment." (PMID 40565233, 2025). "We found that elevated ZC3H13 expression was positively correlated with m6A methylation modification in ESCC tumor tissue." (PMID 40959082, 2025). "The heatmap observations indicated the upregulated expression of all the m6A writers except ZC3H13 in the primary tumor samples compared to the normal tissues." (PMID 38610981, 2024). "Nevertheless, more research is required to explore which biological behaviors of tumor are affected by ZC3H13 and how miR-362-3p/miR-425-5p mediate ZC3H13." (PMID 36875073, 2023). "ZC3H13 activates the NF-κB signaling pathway in patients with this condition to promote tumor proliferation and invasion." (PMID 36133437, 2022). "METTL3, METTL14, METTL16, YTHDC1, YTHDC2, and ZC3H13 expression levels were significantly greater in tumor tissues (p < 0.05)." (PMID 36091006, 2022). "We found that with the exception of RBM15/15B, YTHDF2, ZC3H13, all other regulators were significantly correlated with tumor occurrence (P < 0.05)." (PMID 35572524, 2022). "In the Roessler dataset, by comparing the mRNA expression levels of 22 HCC and 21 normal liver tissues, it was found that ZC3H13 was significantly down-regulated in malignant tumor tissues (p = 1.54E-11, fold change = -3.105)." (PMID 35582419, 2022).
tumor (continued). "Collectively, our findings elucidated that ncRNA-mediated downregulation of ZC3H13 was correlated with a poor prognosis and tumor immune infiltration in HCC." (PMID 35278064, 2022). "The results demonstrated that CBLL1, ELAVL1 and YTHDF1 expressed more in tumor samples than in normal samples of LUAD and LUSC patients, while the expression level of ZC3H13 in tumor samples is lower than in normal samples of LUAD and LUSC patients." (PMID 36261786, 2022). "ZC3H13 has been shown to play a tumor-suppressing role, inhibiting the progression and metastasis of colorectal cancer and breast cancer by regulating the Ras-ERK and Wnt signaling pathways, respectively." (PMID 35945641, 2022). "HNRNPC and YTHDF1 were significantly upregulated in tumor tissues compared with corresponding normal tissues, while ZC3H13, YTHDC2 and METTL14 notably decreased." (PMID 34395102, 2021). "Subsequently, the correlation of the expression level of ZC3H13 was analyzed with ICB genes adjusted by tumor purity to reveal the potential roles of ZC3H13 in ICB treatment." (PMID 34422799, 2021). "In line with the previous results, we found that the expression of ZC3H13 in tumor tissues, higher grade and higher stage was significantly lower." (PMID 34497769, 2021). "It is worth noting that the expression analysis from TCGA-CESC data indicated that ZC3H13 was significantly expressed at lower levels in CESC tumor tissues." (PMID 34497769, 2021). "Our data show that seven m6A regulators (CBLL1, ELAVL1, LRPPRC, RBM15B, YTHDF1, YTHDF2, and ZC3H13) are related to tumorigenesis, tumor microenvironment and tumor prognosis." (PMID 33670062, 2021). "The expression levels of ZC3H13 between tumor samples and normal tissues were detected and compared based on TCGA and GTEx data." (PMID 34422799, 2021). "Compared with tumor samples, the expression level of ZC3H13 was downregulated in adjacent normal tissues." (PMID 34422799, 2021). "The result further confirmed that both METTL14 and ZC3H13 were significantly down-regulated in the nucleus in tumor tissues relative to normal control, which was consistent with the results of bioinformatics analysis on RNA levels." (PMID 33363011, 2020). "To further understand the biology of the three genes, we analyzed the protein expression of IGF2BP1, VIRMA and ZC3H13 in OC in the Clinical Proteomic Tumor Analysis Consortium (CPTAC) samples." (PMID 32950970, 2020). "In our results, the expression of all m6A regulators, except for ZC3H13, is higher in the tumor samples than in the adjacent normal tissue." (PMID 32903675, 2020). "Zhu et al53 found that ZC3H13 acts as a tumor suppressor by regulating activation of the Ras-ERK signaling pathway." (PMID 32742465, 2020). "In PTC, ZC3H13 is downregulated, indicating that ZC3H13 generally has a tumor-suppressive role." (PMID 40243425, 2025). "However, the function of ZC3H13 in ESCC and its impact on tumor-associated macrophages remain poorly understood." (PMID 40959082, 2025). "Silencing ZC3H13 inhibited ESCC tumor growth and M2 macrophage infiltration in mice." (PMID 40959082, 2025). "The results showed that ZC3H13 was downregulated by 64% in tumor tissues." (PMID 38351022, 2024). "In addition, a few studies have suggested that certain writers (METTL3, METTL14, and ZC3H13) exert a tumor-suppressing effect." (PMID 35945641, 2022). "While YTHDF2, RBM15, ZC3H13, METTL3, HNRNPC, YTHDC1 with m6a modifications had higher expression in the low risk group, indicating that they might be tumor suppressors." (PMID 36199800, 2022). "Activation of NF‐κB signaling was confirmed to accelerate tumor proliferation and invasion 30, which suggested that ZC3H13 might be an oncogenic protein." (PMID 35582419, 2022). "ZC3H13 was the only prognostic m6A regulator with downregulated expression level in tumor samples." (PMID 34422799, 2021). "Consistently, ZC3H13 expression level was lower in tumor cells than in liver cells." (PMID 34422799, 2021).